CD163 (CD163 molecule)
Diseases named in the same sentence as CD163 in open-access papers (continued):
Sharing a sentence is not in itself a finding about the gene and the disease.
colon cancer (27 papers, 2010 to 2025). "It was shown that the high level of ccl4 expression had induced tumor-associated macrophages (CD163+ cells) infiltration in colon cancer." (PMID 35463731, 2022). "In contrast, in patients with colon cancer, CD163+ monocyte population was indicative for higher risk of lymphatic metastasis." (PMID 36733385, 2022). "For example, CD68+ and CD163+ macrophages have been demonstrated to exert different effects on the prognosis of stages I-III colon cancer patients, highlighting the importance of characterizing macrophage subtypes in CRC." (PMID 40740776, 2025). "In contrast, in patients with colon cancer CD163+ monocyte population was indicative for LN metastasis development." (PMID 36733385, 2022). "To verify the results above, we compared the expression of RBP‐Jκ and CD163 in colon cancer and normal tissues from 201 patients." (PMID 34655278, 2021). "As high CD163 expression was associated with cancer metastasis, we assessed the effects of CD68+CD163+TAMs on colon cancer cells." (PMID 34655278, 2021). "In our study, we cocultured CD68+CD163+ TAMs with colon cancer cells with different RBP‐Jκ expression." (PMID 34655278, 2021). "The numbers of CD68+ cells were similar in colon cancer tissues of different AJCC stages but the numbers of CD206+ / CD163+ cells were higher in late stage tumors and the number of iNOS+/CD86+ cells was higher in early stage tumors." (PMID 29368606, 2018). "In addition, CD163 expression on macrophages showed significant correlations with Duke’s stage, histologic grade and metastasis in colon cancer." (PMID 39462379, 2024). "In contrast, in patients with colon cancer CD163+ monocytes were indicative for LN metastasis." (PMID 36733385, 2022). "High CD163 expression was observed in 103 cases (51.24%) of colon cancer versus 42 cases (20.90%) of para‐tumour tissues, thus indicating that TAMs had more infiltration in colon cancer tissues (p < 0.001)." (PMID 34655278, 2021). "Moreover, patients with high tumour RBP‐Jκ expression had significantly shorter OS (p < 0.001) and patients with high CD163 expression in colon cancer had a significantly shorter OS (p < 0.001)." (PMID 34655278, 2021). "To further substantiate our data, we carried out immunofluorescence staining with CD163 and AKR1B1 antibodies in FFPE tissues obtained from colon cancer patients." (PMID 40396420, 2025). "Samples and corresponding clinical information of 32 colon cancer patients with lung metastasis were collected, and the CD68, CD163, and SOCS3 status were conducted using immunohistochemistry (IHC)." (PMID 37025997, 2023). "GeoMX DSP-NGS analysis of colon cancer patients identified the correlation of PFKFB3 expression with monocytes infiltration and M2-type polarization markers, including CD163, CD206, CD204 and MARCO." (PMID 36733385, 2022). "Heterogeneity of TAM phenotype was described in different tumour types and at different locations of the same tumour e.g. in colon cancer patients, CD80+, CD86+ and HLA-DR+, as well as CD163+, CD86+, CCR2+ cells were described." (PMID 26838097, 2016). "The infiltration of CD4, CD8, and CD163 in tumor tissues after CXCL1 knockout was not significantly different from that in wild-type colon cancer tissues." (PMID 36434686, 2022). "However, 10 out of 11 patients with colon cancer, with baseline level of CD14-CD16+CD163+ cells below 40% the percentage of this subpopulation was increased up to 18 times." (PMID 36733385, 2022). "Additionally, it was demonstrated that colon cancer cell supernatant induced, in THP-1-derived macrophages, an M2-like phenotype with an increase in CD163 expression." (PMID 25309919, 2014). "By evaluating histological samples from human colon cancer metastases in the liver, we observed that numerous HB-EGF/CXCR4-positive macrophages, which expressed both the M1 CXCL10 and the M2 CD163 markers, indicating a mixed M1/M2 microenvironment, infiltrated metastatic cancer cells." (PMID 20946648, 2010).
colon cancer (continued). "The AOM/DSS group showed weight loss, diarrhea, intestinal shortening, increased number of colon tumors, proliferating tumorigenesis, increased inflammation score, fibrosis, increased CD68+, or CD163+ macrophage cells in the subserosal layer of non-tumor areas." (PMID 33808480, 2021). "Additionally, it has been shown that CAFs from colon cancer promote IL8/CXCR2-mediated monocyte adhesion and attraction through upregulation of VCAM-1 expression and IL-6 production, and subsequently promote polarization to an M2 phenotype by expression of CD163 and CD206." (PMID 38606999, 2024). "In colon cancer patients, high percentage of CD14+CD16- and CD14-CD16+ monocytes expressing CD163 was not changed after surgery." (PMID 36733385, 2022). "In non-neoplastic colonic mucosae as well as colon cancer stroma, TAIs positive for SIRPA, CD68, or CD163 were variably observed." (PMID 33799989, 2021). "The redistribution of CCR2+ and CD163+ monocytes between non-classical subpopulations was found in patients after treatment onset: NAC (for rectal cancer patients) and surgical resection (for rectal and colon cancer patients)." (PMID 36733385, 2022).
lung fibrosis (27 papers, 2015 to 2025). "Higher proportion of S100A9+CD163– cells among CD14+CD16– MNs was found to be associated with lung fibrosis." (PMID 37561593, 2023). "The authors observe that the circulating monocyte/macrophage phenotype could contrast with macrophage signature in tissues such as lung, in which a STAT3-dependent expression of CD163 was associated with pulmonary fibrosis." (PMID 30249259, 2018). "Increased CD14+CD163+CD204+ cells have been found in peripheral blood of patients with SSc, as well as increased markers of macrophage migration and activation (CCL18 and CD163) in microarrays of lung tissue from patients with progressive pulmonary fibrosis." (PMID 35052842, 2022). "To date, the enhanced CD163 expression on alveolar/circulating M2 in ILD such as idiopathic pulmonary fibrosis (IPF) and systemic sclerosis has been demonstrated, respectively." (PMID 36001619, 2022). "M2‐like macrophage markers (CD163 and CD204) and CD163/CD68 and CD204/CD68 cell ratios are significantly elevated in idiopathic pulmonary fibrosis (IPF) patients, associating with shorter overall survival and time‐to‐acute exacerbation in IPF patients." (PMID 33080104, 2020). "On Day 28, the CD163 in the model group showed a more production than that on Day 7; this suggested that CD163 expression continues to increase with the progress of pulmonary fibrosis, while the Schisandra group showed a lower CD163 level." (PMID 32884941, 2020). "The presence of CD163+macrophages was also observed in acute and chronic inflammation, in wound healing sites of SSc patients (with interstitial lung disease) and in a number of pathological conditions, including pulmonary fibrosis." (PMID 27846260, 2016). "Thus, we measured the expression of CD163 in BLM-induced pulmonary fibrosis." (PMID 32884941, 2020). "Research indicates that pro-fibrotic CD163+ macrophages are significantly induced and rapidly accumulate following SARS-CoV-2 exposure, directly contributing to pulmonary fibrosis." (PMID 40963564, 2025). "We previously reported that in lung pathology of ILD in patients with microscopic polyangiitis, chemokine C-C motif ligand 2 (CCL2)-producing CD68+/CD163+ macrophages infiltrate the alveoli, and serum CCL2 levels significantly correlate with the progression of lung fibrosis." (PMID 36077067, 2022). "A pro-fibrotic macrophage phenotype (CD163/LGMN-Mp), expressing high levels of SPP1, recently identified in severe COVID-19 ARDS and IPF (idiopathic pulmonary fibrosis), was absent from CART-BAL, sarcoidosis and HC BALs." (PMID 36720972, 2023). "Given the number of CD206 + macrophages, but not CD163+, CD68+, CD86+ or iNOS+ macrophages, was markedly decreased upon microcystin-LR treatment, it was reasonable to assume that microcystin-LR could meliorate pulmonary fibrosis mainly by suppressing CD206+ M2a-like macrophage differentiation." (PMID 32075954, 2020).
lupus nephritis (27 papers, 2016 to 2026). Glomerulonephritis in the context of systemic lupus erythematosus. "Background/Objectives: We sought to evaluate the clinical predictors of underlying histologic activity in patients with lupus nephritis (LN), with a focus on urinary soluble protein CD163 (usCD163)." (PMID 40943921, 2025). "CD163 is a marker for alternatively activated macrophages, which have been implicated in the pathogenesis of lupus nephritis (LN)." (PMID 32351512, 2020). "Moreover, there was a weak association between serum CD163 concentration and histological activity in lupus nephritis." (PMID 35911758, 2022). "Macrophages are the dominant immune cell type, with CD163+ M2c‐like macrophages predominating in renal biopsies from patients with lupus nephritis." (PMID 40563206, 2025). "Soluble CD163 in urine is a novel and useful biomarker to follow the activity in lupus nephritis and it has emerged as a potential biomarker in systemic sclerosis." (PMID 35693781, 2022). "This is in accordance with our data, establishing the CD163+ macrophages as the dominant renal macrophage subtype in human lupus nephritis." (PMID 27091114, 2016). "While some urine‐based biomarkers for lupus nephritis, such as urinary T cells, CD163, CD206, or IL‐16 have been defined, the diagnosis of lupus nephritis still relies on an invasive kidney biopsy, and none of the investigated biomarkers have been translated into clinical routine." (PMID 40760840, 2025). "CD163-positive macrophages are found in several human glomerular diseases, such as poststreptococcal glomerulonephritis, ANCA-associated vasculitis, diabetic nephropathy, and lupus nephritis (LN)." (PMID 35911758, 2022). "Other study in Lupus nephritis (LN) in mice described an increased CD163+/CD68+cell ratio." (PMID 34307414, 2021). "Moreover, two different M2 macrophages populations, CD163+ and CD206+, were mainly expressed in fibrous crescents and were more common in Lupus nephritis (LN) and ANCA-associated vasculitis than in IgA nephropathy and Henoch Schönlein purpura glomerulonephritis." (PMID 34307414, 2021). "Furthermore, micro-dissected glomeruli from patients with SVV had higher levels of CD163 mRNA expression than those with lupus nephritis, diabetic nephropathy, or nephrotic syndrome, and there was strong expression of CD163 protein in the glomeruli and interstitium of patients with SVV." (PMID 28785984, 2018). "Lupus nephritis kidney sections were costained with the T cell marker CD3, and antibodies to FcRγ and CD163 to spatially localize T cells and infDCs." (PMID 33659005, 2021). "Using immunohistochemical analysis we analyzed renal biopsies from 68 patients with lupus nephritis (ISN/RPS classes II–V) for infiltration with M1-like (iNOS+/CD68+), M2a-like (CD206+/CD68+), M2c-like macrophages (CD163+/CD68+), and FoxP3+ regulatory T-cells." (PMID 27091114, 2016). "The first major finding in our study is that infiltration of macrophage subpopulations differs between the four investigated lupus nephritis ISN/RPS classes and is dominated by CD163+ M2c-like macrophages." (PMID 27091114, 2016). "Urinary soluble CD163 was also elevated in some patients with nonvasculitic forms of glomerulonephritis and was significantly elevated in active lupus nephritis." (PMID 37020541, 2023).
type 2 diabetes (26 papers, 2014 to 2025). "Skeletal muscle tissue from obese individuals or type 2 diabetes patients exhibits the accumulation of anti-inflammatory M2 macrophages on the basis of elevated expression of the CD163 and CD206 proteins." (PMID 39409051, 2024). "The higher protein levels and mRNA gene expression of CD163 were seen in generalized chronic periodontitis subjects with type II diabetes mellitus." (PMID 32656036, 2020). "A recent study observed that CD163 is inversely associated with insulin sensitivity and beta-cell function at OGTT and the risk of dysglycemia in adults at risk for type 2 diabetes." (PMID 32695161, 2020). "Recently soluble CD163 (sCD163), a cleaved form of the macrophage receptor CD163, was identified as a macrophage-specific risk-predictor for developing Type 2 Diabetes." (PMID 24983948, 2014). "Therefore, an increased level of CD163 in our study provides a better understanding of its role in the pathology of periodontal destruction in type II diabetes mellitus." (PMID 32656036, 2020). "Moreover, an increased proportion of CD163+ monocytes has been described in different ARDs such as type 2 diabetes and cancer, lending further support to the hypothesis that healthy aging could be associated with a reduced proportion of M2-monocytes." (PMID 29885276, 2018). "Another study found lower levels of monocyte CD163 expression in patients with type 2 diabetes having vascular complications than in those without vascular complications." (PMID 29445750, 2017). "In the present study, we aimed to quantify CD163 protein levels and its expression in the subgingival plaque samples of generalized chronic periodontitis patients with and without type II diabetes mellitus and correlate it with the amount of periodontal destruction." (PMID 32656036, 2020). "A large prospective study showed that increased serum levels of soluble CD163 (sCD163) could predict future development of type 2 diabetes independent of age and body mass index (BMI)." (PMID 31071174, 2019).
systemic lupus erythematosus (25 papers, 2013 to 2025). An autoimmune multi-organ disease typically associated with vasculopathy and autoantibody production. "In a previous study, we showed that surprisingly, most macrophages in the kidneys of adult lupus patients expressed CD163 and were classified as predominantly M2-like macrophages." (PMID 38331818, 2024). "The studies about the correlation of serum CD163 with systemic lupus erythematosus were conflicting." (PMID 35911758, 2022). "The level of soluble CD163 has been suggested as an indicator for autoimmune disorders such as systemic lupus erythematosus." (PMID 34384354, 2021). "Latest research showed that in systemic lupus erythematosus, the concentration of urinary CD163 can increase hundreds of times when the kidney is involved." (PMID 33997033, 2021). "CD163 is a transmembrane scavenger receptor and is known to be elevated in patients with systemic lupus erythematosus, systemic juvenile idiopathic arthritis, and Kawasaki disease." (PMID 34671607, 2021). "A circulating CD1c+CD14+CD163+ cDC2 subset, related to the DC3s, was found to expand correlatively with disease activity in patients with systemic lupus erythematosus (SLE)." (PMID 34566965, 2021). "On the other hand, the presence of CD163+CD14+ infDCs in the patients with circulation of lupus suggests that infDC from the peripheral circulation enter the kidney in LN." (PMID 33659005, 2021). "One study revealed that CD163+CD14+ DC3s were significantly increased within the CD5− DC subset exclusively in systemic lupus erythematosus (SLE) patients which correlated with disease severity." (PMID 40584260, 2025). "The subsequent studies phenotypically characterized the DC3 population as CD163+CD14+ DCs that accumulate in the blood of patients with systemic lupus erythematosus (SLE)." (PMID 37520521, 2023). "Some researchers believe that VaD may be linked to systemic autoimmune diseases, and through bioinformatics and ML methods, genes such as C1QA, CD163, LY96, and MS4A4A have been identified as potential biomarkers for the link between VaD and systemic lupus erythematosus." (PMID 39116438, 2024). "They revealed high heterogeneity of myeloid cells with expansion of a specific cDC2 subset characterized by expression of CD163 and CD14 and correlating with systemic lupus erythematosus (SLE) progression." (PMID 32849606, 2020). "Differential expression of CD163 and CD14 marks different stages of maturation and activation in DC3, and an increased frequency of CD163+ CD14+ blood DC3 with proinflammatory function exists in patients with active systemic lupus erythematosus (SLE)." (PMID 34614036, 2021).
AIDS (24 papers, 2010 to 2026). A syndrome resulting from the acquired deficiency of cellular immunity caused by the human immunodeficiency virus (HIV). "In RMs, the frequencies of CD163+ macrophages increased four-fold during SIV infection associated with progression to AIDS." (PMID 36389795, 2022). "We examined the effect of HCV cure on markers of macrophage activation and microbial translocation (soluble CD163 and sCD14 respectively) which have been implicated in the pathogenesis of serious non‐AIDS morbidities." (PMID 31339004, 2019). "Bregs, CD8+CD20+ T-cells, CD8+CD14+ T-cells, and M2-like CD14+CD163+ monocytes may serve as early indicators of immune dysfunction in PWH at risk for developing AIDS-NHL, potentially months to years before diagnosis, as this cohort study suggests." (PMID 41148820, 2025). "The microglial/macrophage activation markers CD68 and CD163 were occasionally immunodetected in the cerebellum of the control and SIV/-AIDS macaques." (PMID 27737697, 2016). "The number of CD163+ cells was also reduced by 6-Cl-ddG but was still increased in comparison to control and SIV/-AIDS group." (PMID 27737697, 2016).